RAC1 (Rac family small GTPase 1)
Diseases named in the same sentence as RAC1 in open-access papers (continued):
Sharing a sentence is not in itself a finding about the gene and the disease.
leukemia (30 papers, 2008 to 2025). A malignant (clonal) hematologic disorder, involving hematopoietic stem cells and characterized by the presence of primitive or atypical myeloid or lymphoid cells in the bone marrow and the blood. "In contrast, overexpression of Rac1 increases cell migration and proliferation potential of leukemic cells, which could be implicated in leukemia development and progression." (PMID 29228706, 2017). "We investigated the inhibition of the signaling molecule ras-related C3 botulinum toxin substrate 1 (Rac1) in leukemia cells derived from 79 consecutive AML patients, using five Rac1 inhibitors: ZINC69391, ITX3, EHOP-016, 1A-116, and NSC23766." (PMID 36009428, 2022). "Taken together, these observations clearly show that Rac1 plays an important role in adhesion, migration, engraftment, and dissemination of leukemia/lymphoma cells." (PMID 30558116, 2018). "The rationale that led us to explore this cancer indication was based in evidence showing that Rac1 is over-expressed in leukemia patients." (PMID 29228706, 2017). "In fact, Rac1 is active, overexpressed in chronic and acute myeloid leukemia patients and promotes leukemia development through enhancing leukemia cells’ homing and retention in niche." (PMID 29262589, 2017). "Active BCR related (ABR) gene deactivates ras-related C3 botulinum toxin substrate 1 (RAC1), which plays an essential role in regulating normal hematopoiesis and in leukemia." (PMID 29262589, 2017). "In agreement, it has been previously suggested that transformed cells become addicted to Rac1 signaling for survival and leukemia maintenance." (PMID 29228706, 2017). "Further, it is shown that the inactivation of the known ABR target Rac1 in leukemia increases chemotherapy-induced apoptosis, supporting a possible mechanism of ABR action in AML therapy via inhibition of Rac1." (PMID 29262589, 2017). "The siRNA-mediated knockdown of Rac1 expression in leukemia cell lines proved to inhibit cell proliferation, migration and colony formation." (PMID 29228706, 2017). "In order to specifically address the role of either RAC1 or RAC2 in human leukemia, we used shRNA interference strategy." (PMID 26016997, 2015). "Studies show that bufalin induce leukemia cell apoptosis by activating cdc2 kinase, casein II, protein kinase A, and protein kinase C, AP-1 and Rac1." (PMID 23110625, 2012). "Rac1 activation was markedly induced following heparanase addition to ARF-77 leukemia F cells (Hepa)." (PMID 18545691, 2008). "Rac1 inhibition enhances leukemia cell sensitivity to etoposide-induced apoptosis." (PMID 39941828, 2025). "However, some leukemia/lymphoma cells have found a way to modulate Rac1 activity by upstream regulators, such as CD9 in B-ALL and CADM1 in ATL." (PMID 30558116, 2018). "However, in already fully transformed murine MA9 leukemia cells, depletion of either Rac1 or Rac2 reduced the in vitro survival through enhanced apoptosis." (PMID 30558116, 2018). "Recent studies have demonstrated that Wnt5a could induce activation of Rac1 in leukemia cells of patients with CLL via a ROR1-dependent pathway, which could not be inhibited by ibrutinib." (PMID 29872501, 2018). "From a translational perspective, combining anthracycline drugs and α2β1 integrin blockers or the design of novel agents that can induce leukemia cell death independently from the Rac1 pathway might be helpful in preventing the emergence of drug-resistant leukemic cells." (PMID 31857649, 2019). "Our data indicated that Rac1 is an important pathway in doxorubicin-induced apoptosis of leukemia cells raising the question whether it is a targeted-event in collagen-mediated doxorubicin resistance in leukemia." (PMID 31857649, 2019). "Interestingly, KMT2A-MLLT3 leukemias lacking a constitutively expressed signaling mutation, sustain or upregulate intracellular signaling pathways, such as RAC1 and MAPK, potentially as a contributing oncogenic event." (PMID 29720585, 2018).
leukemia (continued). "In leukemia, the Cobbl1/SH3BP1/PACSIN2 axis promotes drug resistance and progression of chronic myeloid leukemia by regulating Rac1 activity, while the expression level of SH3BP1 is inversely correlated with the prognosis of acute myeloid leukemia." (PMID 40688112, 2025). "This resulted in the downregulation of several pathways of angiogenesis (FAS, TRAIL, IFN-γ, TNF receptor, and RAC1) in MCF-7 and human Jurkat leukaemia cells." (PMID 38371392, 2024). "Transcriptomic profiling and molecular biological analyses suggest that CBAP acts upstream of Ras and Rac1, and functions as a modulator of both Raf-MEK–ERK and Akt-mTORC1 signaling pathways to control leukemia cell growth." (PMID 30266989, 2019). "Accordingly, by inhibiting Rac1, collagen/α2β1 integrin signaling inhibits drug-induced DNA damage and JNK activation, restores Mcl-1 levels thereby promoting leukemia chemoresistance." (PMID 31857649, 2019). "Conversely, another study found that treatment of leukemia B cells with NSC-23766, an inhibitor of activated Rac1, enhanced the capacity of Bcl-2 antagonists to induce apoptosis." (PMID 29872501, 2018). "We examined primary neoplastic cells of patients with MCL who had circulating leukemia cells for Wnt5a-induced, ROR1-dependent activation of Rac1." (PMID 29872501, 2018). "In an AML mouse model in which the leukemia was induced by transplanted murine AE9a (AML1-ETO9a)-transfected c-kit+ HSPCs, active Rac1 (Rac1V12) enhances homing and engraftment into the BM." (PMID 30558116, 2018). "Rac1, 2 and 3 are also involved in BCR-ABL-mediated signaling pathway in HSC and leukemia stem cells." (PMID 28160553, 2017). "Furthermore, as reported in a previous study, Rac1 activation promoted FGFR1-mediated leukemia occurrence in the stem cell leukemia syndrome, while Rac1 promoted HSPC expansion in initiating and maintaining leukemia in the mouse model." (PMID 36923939, 2023). "Moreover, the activation of the Rac1 pathway leads to TKI resistance at the cellular level and promotes migration and self‐renewal of hematopoietic stem cells, participating in leukemia initiation and maintenance." (PMID 35352878, 2022). "Despite the fact that knocking down either RAC1 or RAC2 is adequate to reduce the transformed MLL-AF9 leukemia development; RAC2 but not RAC1, plays a dominant role in the initiation of acute myeloid leukemia in vivo." (PMID 33406731, 2021). "Knock out mice for Rac1 or Rac2 was sufficient to impair the survival and growth of MLL-AF9 leukemia and this could be rescued by Bcl-xl with the BH3-mimetric ABT-737." (PMID 32529062, 2020). "Notably, the leukemia-promoting action of TNFAIP8 was mediated by sustaining activity of the ERK signaling pathway, through an interaction with Rac family small GTPase 1 (Rac1)." (PMID 32795319, 2020). "Deletion of Rac2 alone, but not of Rac1, delayed leukemia onset and increased the survival of the mice significantly." (PMID 30558116, 2018). "Notably, disruption of the dCS region of DOCK2 or use of dominant‐negative mutant DOCK2–dCS significantly inhibits Rac1 activation, showing potential therapeutic value for leukemia and immune diseases." (PMID 41020039, 2025). "However, the role of RAC1 in the efficacy of FLT3 inhibitors in the treatment of FLT3-ITD leukemia has not yet been determined." (PMID 34172833, 2021). "Lastly, it has been reported that α2β1 integrin and collagen I participate to doxorubicin-induced drug resistance in leukemia by either protecting leukemia cells from apoptosis through MAPK/ERK pathway activation, or by decreasing the DNA damage through the inhibition of Rac1 activation." (PMID 33014790, 2020). "Interestingly, Rac1 inhibition selectively induced apoptosis on patient-derived leukemia cells but not on normal mononuclear cells." (PMID 29228706, 2017).
leukemia (continued). "Activation of alternative pathways, such as KRAS/RAC1/ROS/NLRP3, in leukemia cells or non-hematopoietic cells may also lead to the production of pro-inflammatory IL-1β that promotes leukemia cell proliferation in an autocrine fashion." (PMID 35460465, 2022).
cardiac hypertrophy (29 papers, 2012 to 2025). "Loss of Rac1 S-palmitoylation at Cys-178 results in more severe cardiac hypertrophy and functional decompensation in response to chronic cardiomyocyte AT1R signaling." (PMID 40924486, 2025). "Cardiomyocyte-specific deletion of Rac1 protected mice from AngII-induced cardiac hypertrophy, which was associated with reduced NOX2 activity and superoxide production as well as reduced ASK1/NFκB activation." (PMID 41333012, 2025). "Loss of Rac1 S-palmitoylation at Cys-178 results in more severe cardiac hypertrophy and functional decompensation in response to AngII infusion or pressure overload." (PMID 40924486, 2025). "In contrast, gene transfer of the dominant-negative mutant Rac1(N17) suppresses pressure overload-stimulated cardiac hypertrophy, and cardiomyocyte-specific deficiency of Rac1 in mice reduces angiotensin-II-induced oxidative stress and myocardial hypertrophy." (PMID 37524688, 2023). "Overexpression of constitutively active Rac1 results in lethal dilated cardiomyopathy and arrhythmogenesis, while loss of Rac1 in cardiomyocytes ameliorates angiotensin II–induced cardiac hypertrophy and oxidative stress." (PMID 37926281, 2023). "As an upstream activator of MEK-ERK signaling, RAC1 has also been implicated in pathological cardiac hypertrophy and activated by DEF6 in the immune system and cell morphology modification." (PMID 37524688, 2023). "Constitutive activation of Rac1 in vivo has also been shown to enhance the spontaneous development of cardiac hypertrophy, with mice being more susceptible to ischemic injury with notable increases in myocardial infarcted areas." (PMID 27442895, 2017). "Atorvastatin and pitavastatin were shown to reduce membrane-associated Rac1 and active Rac1 levels in response to AngII infusion in rats and treatment with simvastatin or atorvastatin reduced the degree of cardiac hypertrophy in mice subjected to left ventricular pressure overload by TAC." (PMID 41333012, 2025). "The top predicted pathways for miR-142-3p include molecular mechanisms of cancer, cardiac hypertrophy signaling, and protein kinase A signaling, and one target for miR-142-3p is RAC1, which is implicated in cancer, viral infection, and in brain and myocardium ischemic injury." (PMID 38272952, 2024). "Statins have been shown to reduce Rac1 activity in cardiomyocytes and protect against AngII or pressure overload-induced cardiac hypertrophy in vivo." (PMID 41333012, 2025). "To investigate the role of Rac1 S-palmitoylation in a mouse model of pathologic cardiac hypertrophy, we implanted osmotic minipumps to chronically infuse either saline or AngII (3 mg/kg/day) for 2 weeks." (PMID 40924486, 2025). "PKM2 was found to interact with Rac1 in cardiomyocytes and PKM2 deficiency worsened TAC-induced cardiac hypertrophy." (PMID 41333012, 2025). "Among genes where changes in AS rewire interactions with these pathways, we found RAC1 (Rac Family Small GTPase 1), which is involved in cardiac hypertrophy and heart failure onset." (PMID 40337913, 2025). "Several studies have identified roles of proteins that interact with Rac1 in the development of cardiac hypertrophy." (PMID 41333012, 2025). "The key role of gene-based regulatory mechanisms: “ZDHHC3 and ZDHHC7, localized in the Golgi apparatus, have been identified as key regulatory factors in cardiac hypertrophy because they participate in the palmitoylation process of RAC1." (PMID 40969373, 2025). "Conversely, cardiomyocyte-specific deletion or knockdown of Rac1 protects against cardiac hypertrophy in response to AngII infusion or left ventricular pressure overload induced by transverse aortic constriction (TAC), respectively." (PMID 40924486, 2025). "Pak proteins are canonical effectors of Rac1 and cardiomyocyte-specific deletion of either Pak1 or Pak2 phenocopies exacerbated cardiac hypertrophy and dysfunction in response to pressure overload or AngII infusion that we observed in Rac1cKI mice." (PMID 40924486, 2025).
cardiac hypertrophy (continued). "Because global deletion of Rac1 in mice is embryonically lethal, cardiomyocyte-specific Rac1 knockout mice were generated to assess the necessity of cardiomyocyte Rac1 signaling in cardiac hypertrophy." (PMID 41333012, 2025). "A second model of hyperactive Rac1 signaling was developed by expressing a constitutively active corn Rac transgene, ZmRacD, in mice, which also resulted in cardiac hypertrophy and reduced systolic function with age." (PMID 41333012, 2025). "These include the Rac1-mediated inhibition of NADH oxidase activity and downregulation of angiotensin AT1 receptor expression and inhibition of cardiac hypertrophy through an antioxidant mechanism involving the inhibition of Rac1 geranylgeranylation." (PMID 38540212, 2024). "In another rat model of HFpEF (transgenic rats overexpressing the renin gene with elevated cardiac levels of angiotensin II), rosuvastatin significantly reduced Rac1 expression, cardiac hypertrophy, and perivascular fibrosis, and improved LV contractility." (PMID 38732177, 2024). "Many previous studies have confirmed the involvement of Rac1-MEK-ERK1/2 signaling cascade in cardiac hypertrophy." (PMID 37524688, 2023). "Rac1 plays fundamental roles in cardiac homeostasis and pathophysiology and is necessary and sufficient to induce cardiac hypertrophy and arrhythmia." (PMID 37926281, 2023). "Further investigation identified Rac1 as a target of zDHHC3 in the heart, and both Zdhhc3 and Zdhhc7 were shown to be important in the initiation of cardiac hypertrophy with pressure overload stimulation." (PMID 37926281, 2023). "A recent study revealed that STEAP3 ameliorates pathological cardiac hypertrophy by blocking the Rac1-MEK-ERK1/2 signaling cascade." (PMID 37524688, 2023). "Many previous studies had connected Rac1-mediated cardiac hypertrophy and the MEK1/2-ERK1/2 signaling pathway activation." (PMID 37524688, 2023). "To conclude, activation of Rac1-MEK-ERK signaling cascades is some of the mechanisms by which DEF6 accelerates the development of pathological cardiac hypertrophy." (PMID 37524688, 2023). "For example, cardiomyocyte-specific Rac1 knockout mice (c-Rac1) demonstrated an essential requirement for RAC1 in cardiac hypertrophy." (PMID 37895289, 2023). "In this regard, scoparone was reported to inhibit Ang II-induced cardiac hypertrophy in vitro via the elimination of overexpression of RAC1 and by inhibiting RAC1-mediated oxidative stress." (PMID 36359731, 2022). "Both in vitro and in vivo findings showed that the RAC1 inhibition was effective in alleviating oxidative stress in cardiac cells, thereby resulting in an attenuation of cardiac hypertrophy and dysfunction." (PMID 35574363, 2022). "In cardiac hypertrophy, hyperglycemia, and failing human myocardium, RAC1 plays an important role in regulating the myocardial superoxide production." (PMID 35574363, 2022). "This role in hypertrophy is associated with Rac1′s unique function among the Rho family members to increase the NADPH oxidase activity and thus increase oxidative stress, and as result, exacerbate cardiac hypertrophy." (PMID 36077014, 2022). "Taken together, these findings suggested that abnormal expression of PRR/RAC1 was related to the pathogenesis of cardiac hypertrophy and cardiac dysfunction in DOX induced HF." (PMID 35574363, 2022). "We also demonstrate that SCO‐mediated inhibition of RAC1 alleviates Ang II‐induced cardiac hypertrophy and fibrosis in vitro and in vivo." (PMID 33560596, 2021). "Activation of RAC1 is required for Ang II‐induced cardiac hypertrophy, fibrosis and intracellular oxidation in adult hearts." (PMID 33560596, 2021). "Activation of ras‐related C3 botulinum toxin substrate 1 (RAC1) by angiotensin II (Ang II) plays a pivotal role in myocardial hypertrophy." (PMID 33560596, 2021). "In this study, we provide evidence that LAPTM5 also plays an important role in cardiac hypertrophy via the Rac1-MEK-ERK1/2 pathway." (PMID 34692792, 2021).